DNAI7 (dynein axonemal intermediate chain 7)
Description:
Via its association with the multisubunit axonemal dynein complex, is potentially involved in the regulation of cilia function. May also act as a cell cycle regulator.
Synonyms: CASC1; CFAP94; LAS1; PPP1R54; FLJ10921
Tractability: Small molecule: a structure with a bound ligand is known. PROTAC: UniProt records ubiquitination sites on it.
Gene: Protein-coding gene on chromosome 12 (25,108,289 to 25,195,163, reverse strand). Ensembl gene ENSG00000118307.
Subcellular location: Cell projection, cilium; Cytoplasm
Subcellular location (Human Protein Atlas): Cytosol; Vesicles
Gene Ontology:
Molecular function: protein binding; beta-tubulin binding; microtubule binding
Cellular component: axonemal dynein complex; axoneme; cilium; cytoplasm
Genetic constraint (gnomAD): Loss-of-function variants: 38 observed, 38.84 expected, observed/expected ratio (o/e) 0.98, 90% interval 0.75 to 1.28. The upper end of that interval is the gene's LOEUF score, 1.28, which puts it in group 5 of 6, group 1 being the genes least tolerant of losing a copy. Missense variants: 406 observed, 451.51 expected, observed/expected ratio (o/e) 0.9, 90% interval 0.83 to 0.98. Synonymous variants: 157 observed, 156.43 expected, observed/expected ratio (o/e) 1, 90% interval 0.88 to 1.15.
Homologues: Orthologues: chimpanzee DNAI7 (96% identical), macaque DNAI7 (95% identical), dog DNAI7 (81% identical), pig DNAI7 (79% identical), rabbit DNAI7 (76% identical), guinea pig DNAI7 (72% identical), mouse Dnai7 (67% identical), rat Dnai7 (67% identical), tropical clawed frog dnai7 (44% identical), zebrafish dnai7 (39% identical), Drosophila melanogaster CG15373 (23% identical), Drosophila melanogaster CG33286 (18% identical), and 3 more.
Diseases named in the same sentence as DNAI7 in open-access papers:
DNAI7 is named in the same sentence as 11 diseases in open-access papers, as found by Europe PMC text mining. Sharing a sentence is not in itself a finding about the gene and the disease.
DNAI7 shares sentences with these, for which no sentence is quoted: cancer (5 papers); adenoma (2); tumor (2); adenocarcinoma (1); Bladder Cancer (1); infection (1); lung adenocarcinoma (1); lung carcinoma (1); nasopharyngeal neoplasm (1); primary ciliary dyskinesia (1); synucleinopathy (1).